ATP8B1 (ATPase phospholipid transporting 8B1)
Description:
Catalytic component of a P4-ATPase flippase complex which catalyzes the hydrolysis of ATP coupled to the transport of phospholipids, in particular phosphatidylcholines (PC), from the outer to the inner leaflet of the plasma membrane. May participate in the establishment of the canalicular membrane integrity by ensuring asymmetric distribution of phospholipids in the canicular membrane (By similarity). Thus may have a role in the regulation of bile acids transport into the canaliculus, uptake of bile acids from intestinal contents into intestinal mucosa or both and protect hepatocytes from bile salts (By similarity). Involved in the microvillus formation in polarized epithelial cells; the function seems to be independent from its flippase activity. Participates in correct apical membrane localization of CDC42, CFTR and SLC10A2. Enables CDC42 clustering at the apical membrane during enterocyte polarization through the interaction between CDC42 polybasic region and negatively charged membrane lipids provided by ATP8B1 (By similarity). Together with TMEM30A is involved in uptake of the synthetic drug alkylphospholipid perifosine. Required for the preservation of cochlear hair cells in the inner ear (By similarity). May act as cardiolipin transporter during inflammatory injury (By similarity).
Synonyms: ATPIC; FIC1; PFIC; BRIC; ICP1; PFIC1
Tractability: Small molecule: a structure with a bound ligand is known. Antibody: UniProt places it where antibodies can reach, with high confidence; its Gene Ontology location is reachable by antibodies, with high confidence; UniProt predicts a signal peptide or a membrane-spanning region; the Human Protein Atlas places it where antibodies can reach. PROTAC: its protein half-life has been measured.
Gene: Protein-coding gene on chromosome 18 (57,646,426 to 57,803,560, reverse strand). Ensembl gene ENSG00000081923.
Subcellular location: Cell membrane; Apical cell membrane; Cell projection, stereocilium; Endoplasmic reticulum; Golgi apparatus
Subcellular location (Human Protein Atlas): Cytosol; Plasma membrane; Nuclear bodies; Nucleoplasm
Pathways (Reactome):
Transport of small molecules: Ion transport by P-type ATPases
Gene Ontology:
Molecular function: ATPase-coupled intramembrane lipid transporter activity; phosphatidylcholine flippase activity; phosphatidylcholine floppase activity; phosphatidylserine floppase activity; protein binding; phosphatidylserine flippase activity; aminophospholipid flippase activity; ATP binding; ATP hydrolysis activity; cardiolipin binding; flippase activity; lipid transporter activity; magnesium ion binding; nucleotide binding
Biological process: apical protein localization; negative regulation of DNA-templated transcription; phospholipid translocation; regulation of chloride transport; regulation of microvillus assembly; xenobiotic transmembrane transport; bile acid and bile salt transport; Golgi organization; monoatomic ion transmembrane transport; aminophospholipid translocation; aminophospholipid transport; inner ear receptor cell development; phospholipid transport; regulation of plasma membrane organization; sensory perception of sound; transmembrane transport; vestibulocochlear nerve formation
Cellular component: apical plasma membrane; endoplasmic reticulum; Golgi apparatus; phospholipid-translocating ATPase complex; plasma membrane; trans-Golgi network; endomembrane system; membrane; stereocilium
Genetic constraint (gnomAD): Loss-of-function variants: 77 observed, 150.2 expected, observed/expected ratio (o/e) 0.51, 90% interval 0.43 to 0.62. The upper end of that interval is the gene's LOEUF score, 0.62, which puts it in group 2 of 6, group 1 being the genes least tolerant of losing a copy. Missense variants: 1,209 observed, 1,571.1 expected, observed/expected ratio (o/e) 0.77, 90% interval 0.73 to 0.81. Synonymous variants: 526 observed, 574 expected, observed/expected ratio (o/e) 0.92, 90% interval 0.85 to 0.99.
Homologues: Orthologues: chimpanzee ATP8B1 (99% identical), macaque ATP8B1 (98% identical), pig ATP8B1 (95% identical), mouse Atp8b1 (94% identical), rabbit ATP8B1 (94% identical), dog ATP8B1 (94% identical), rat Atp8b1 (94% identical), guinea pig ATP8B1 (83% identical), tropical clawed frog atp8b1 (75% identical), zebrafish atp8b1 (67% identical), Drosophila melanogaster CG4301 (29% identical), Drosophila melanogaster CG9981 (28% identical), and 3 more. Paralogues in human: ATP8B4 (52% identical), ATP8B2 (51% identical), ATP8B3 (45% identical), ATP8A2 (38% identical), ATP8A1 (38% identical), ATP10D (34% identical), ATP10A (34% identical), ATP10B (33% identical), ATP11B (31% identical), ATP11A (31% identical), ATP11C (29% identical), ATP9B (26% identical), and 1 more.
Diseases named in the same sentence as ATP8B1 in open-access papers:
ATP8B1 is named in the same sentence as 104 diseases in open-access papers, as found by Europe PMC text mining. Sharing a sentence is not in itself a finding about the gene and the disease. The quoted sentences say what the papers report.
cholestasis (43 papers, 2008 to 2026). Impairment of the bile flow caused by obstruction within the liver, or outside the liver in the bile duct system. "Mutations in the ATP8B1 gene lead to impaired bile flow, also known as cholestasis, which can result in extensive liver damage." (PMID 38382846, 2024). "Results in these two patients are consistent with the positive outcomes previously reported in patients with episodic cholestasis and ATP8B1 mutations who were treated with odevixibat." (PMID 39768432, 2024). "Studies on mice with ATP8B1 gene mutations have shown that their liver cells have reduced ability to transport hydrophobic bile acids, which can lead to cholestasis." (PMID 37324459, 2023). "Here, we report a 17-year-old patient with cholestasis who has a rare heterozygous ATP8B1 gene mutation (p.T888K)." (PMID 35783636, 2022). "Patient numbers 2 and 3 possessed rare, heterozygous variants in ATP8B1: p.Ile349Thr and p.Asn45Thr, respectively; the latter has been found previously by others to be associated with cholestasis." (PMID 28626473, 2017). "ATP8B1 deficiency reduces cholesterol contents in the canalicular membrane, which impairs the activities of the bile salt export pumps, further causing the cholestasis." (PMID 28899357, 2017). "The mechanism by which loss in ATP8B1 leads to cholestasis is poorly understood, but it has been proposed that increased PS on the luminal leaflet on canalicular membranes due to the loss in ATP8B1 flippase activity results in abnormal lipid packing." (PMID 27458383, 2016). "Progressive familial intrahepatic cholestasis type 1 (PFIC1), an inherited liver disease caused by mutations in ATP8B1, progresses to severe cholestasis with a sustained intractable itch." (PMID 25022842, 2014). "Our laboratory has extensively studied the etiology of ATP8B1-associated cholestasis using knock-in mice for a prototypic PFIC1 mutation, a glycine-to-valine substitution at amino acid 308 that results in near complete absence of the protein (G308V)." (PMID 23579954, 2013). "Since ATP8B1 deficiency is primarily characterised by cholestasis, some studies attempted to attribute the phenotype to a defective farnesoid X receptor (FXR) signalling pathway." (PMID 23251605, 2012). "Since ATP8B1 deficiency is associated with cholestatic liver disease, most studies have focused on the role of the gene in cholestasis." (PMID 23251605, 2012). "Mutations in ATP8B1 gene were identified as a cause of low γ-glutamyltranspeptidase cholestasis with variable phenotype, ranging from Progressive Familial Intrahepatic Cholestasis to Benign Recurrent Intrahepatic Cholestasis." (PMID 23251605, 2012). "The etiology of ATP8B1-associated cholestasis has been extensively covered elsewhere." (PMID 38382846, 2024). "The region on chromosome 18 contains 2 genes of particular interest, by functional and disease criteria: ATP8B1, mutated in some forms of cholestasis, and CCBE1 (collagen and calcium-binding epidermal growth factor domain-containing protein-1), essential for lymphangiogenesis in zebrafish and mouse." (PMID 24086631, 2013). "An alternative hypothesis for the etiology of ATP8B1-associated cholestasis is based on findings that ATP8B1 deficiency impairs farnesoid X Receptor (FXR)-dependent signaling." (PMID 23579954, 2013). "Of these, MYO5B-associated cholestasis (OMIM#619868) emerges as a considerable group, estimated to represent up to 25% of FIC cases other than those caused by variations in the ATP8B1, ABCB11 and ABCB4 genes." (PMID 41511375, 2026). "PFIC can present in an episodic form characterized by intermittent cholestatic attacks; episodic cholestasis can also be caused by mutations in PFIC-associated genes (e.g., ATP8B1 and ABCB11)." (PMID 39768432, 2024). "Mutations in genes encoding bile transport proteins such as ATP8B1 (PFIC1) and ABCB11 (PFIC2), and tight junction protein ZO-2 (PFIC4), can disrupt bile flow regulation and contribute to cholestasis." (PMID 39322562, 2024).
cholestasis (continued). "These mutations are thought to affect the tubular membrane localization of ATP8B1, leading to impaired bile acid transport and cholestasis." (PMID 37324459, 2023). "Mutations in BRIC (ATP8B1 and ABCB11) cause cholestasis by disrupting the Bile Salt Export Pump (BSEP), which transports bile to the canaliculi." (PMID 35310310, 2022). "The risk of cholestasis in pregnancy has been associated with genetic variants in ABCB4, ABCB11, ATP8B1, ABCC2, and TJP2 genes." (PMID 34557220, 2021). "Increased concentrations of plasma alkaline phosphatase, total bile salts and bilirubin confirmed the presence of cholestasis in Atp8b1 mutant mice (p < 0.01)." (PMID 33731871, 2021). "One of the diseases leading to cholestasis in humans is progressive familial intrahepatic cholestasis type I (PFIC I), which is caused by a mutation in the ATP8B1 gene." (PMID 33731871, 2021). "In order to mimic cholestasis of pregnancy, WT and Atp8b1 mutant mice were also studied during pregnancy (n = 6 and 7 females, respectively) with the latter group fed a 0.1% CA diet from day 12 of the pregnancy onwards." (PMID 33731871, 2021). "In fact, Atp8b1 mutant mice scratched less during cholestasis (41% of baseline, p = 0.005) and cholestatic pregnancy (27% of baseline, p = 0.001)." (PMID 33731871, 2021). "Simultaneous induction of cholestasis with 0.1% CA in Atp8b1 mutant mice transduced with AAV8-CMV-ATX further induced plasma ATX activity but still, long-term scratch activity decreased compared to non-cholestatic animals." (PMID 33731871, 2021). "Marked cholestasis was accomplished in both Atp8b1 mutant mice on a CA-supplemented diet and in ANIT-treatment in WT mice, but scratch activity was decreased rather than increased while plasma ATX activity was increased." (PMID 33731871, 2021). "Defects in genes coding for bile salt transporter proteins (BSEP/ABCB11, FIC1/ATP8B1 and MDR3/ABCB4) cause cholestasis leading to the release of inflammatory cytokines, chronic inflammation and subsequent cholangiocarcinogenesis." (PMID 30819129, 2019). "Mutations in ATP8B1 (PFIC1/FIC1 deficiency) and ABCB11 (PFIC2/BSEP deficiency) may cause either BRIC1/BRIC2 or progressive cholestasis with severe pruritus." (PMID 41601986, 2026). "ATP8B1 has been extensively studied for its role in cholestasis; however, these patients may experience extra-hepatic symptoms, including hearing loss." (PMID 38382846, 2024). "Although several pathogenic models focusing on hepatic ATP8B1 function have been proposed for cholestasis in PFIC19,20–22, no effective therapy has yet been developed." (PMID 37990006, 2023). "In addition to familial intrahepatic cholestasis, partial defects in ATP8B1, ABCB11, and ABCB4 predispose patients to drug-induced cholestasis and intrahepatic cholestasis in pregnancy." (PMID 30148122, 2018). "Genetic defects in ATP8B1 or ABCB11 account for the majority of cholestasis with low GGT." (PMID 27050426, 2016). "More studies are needed to further define the role of ATP8B1 in cholestasis." (PMID 27458383, 2016). "Moreover, Atp8b1-deficient mice display an increase in the biliary extraction of cholesterol from the canalicular (apical) membrane of hepatocytes, affecting the activity of the bile salt transporter, ABCB11, and resulting in cholestasis." (PMID 38382846, 2024). "Thus, in pre-LTx PFIC1 patients, severe cholestasis protectively alters PC dynamics against the lack of hepatic PC due to dysfunction of ATP8B1 in the IEC and subsequent choline deficiency and suppresses the development of steatohepatitis." (PMID 37990006, 2023). "Unlike PFIC1 patients, these mice do not develop cholestasis unless challenged with cholate, allowing us to examine ATP8B1 deficiency without the confounding effects of liver injury." (PMID 40851490, 2025). "This is supported by previous findings that Atp8b1G308V/G308V mice homozygous for an ortholog of the ATP8B1 mutant in PFIC1 patients exhibit cholestasis, but not steatosis." (PMID 37990006, 2023).
cholestasis (continued). "To verify that the reduction of cholestasis-induced itch is not a specific result of the Atp8b1 mutant mouse model, we also tested a second cholestatic model." (PMID 33731871, 2021). "During the present study, we discovered a decreased rather than increased scratch activity in Atp8b1 mutant mice as well as in ANIT-treated WT mice during cholestasis." (PMID 33731871, 2021). "Our present study shows that cholestasis in Atp8b1 mutant mice led to a decreased rather than increased scratch activity." (PMID 33731871, 2021). "To study pruritus in mice, we measured scratch activity in cholestatic Atp8b1 mutant mice, a model for Progressive Familial Intrahepatic Cholestasis type 1, and wild type mice (WT) with alpha-naphthylisothiocyanate (ANIT)-induced cholestasis." (PMID 33731871, 2021). "Together, these results indicate that in mice, cholestasis does not induce pruritus (at least not in Atp8b1 mutant mice and ANIT-treated mice) and enhanced plasma ATX activity does not translate into increased scratch activity under the chosen experimental conditions." (PMID 33731871, 2021).
progressive familial intrahepatic cholestasis type 1 (29 papers, 2009 to 2025). PFIC1, a type of progressive familial intrahepathic cholestasis (PFIC), is an infantile hereditary disorder in bile formation that is hepatocellular in origin and associated with extrahepatic features. "Progressive familial intrahepatic cholestasis type 1 (PFIC1) is an autosomal recessive cholestatic liver disease caused by mutations in ATP8B1, which encodes a phospholipid translocase with a broad substrate specificity." (PMID 40851490, 2025). "Patients with mutations in ATP8B1 develop progressive familial intrahepatic cholestasis type 1 [PFIC1], a severe liver disease that requires life-saving liver transplantation." (PMID 38366839, 2024). "PFIC type 1, also known as Byler disease, is caused by defects in the ATP8B1 gene on chromosome 18 (18q21), which produces the FIC1 protein, a “flippase” that protects the structural integrity of the membrane." (PMID 38275473, 2024). "PFIC1, also known as Byler’s disease, is a rare disorder caused by mutations or deletions in the ATP8B1 gene." (PMID 37324459, 2023). "Mutations in the gene encoding ATP8B1 cause progressive familial intrahepatic cholestasis type 1 (PFIC1), an extremely rare inherited autosomal recessive liver disease." (PMID 37990006, 2023). "ATP8B1 is a phospholipid flippase that is deficient in patients with progressive familial intrahepatic cholestasis type 1 (PFIC1)." (PMID 36293199, 2022). "These included recurrent disease-causing variants for glycogen storage disease IIIa/IIIb (AGL), progressive familial intrahepatic cholestasis type 1 (ATP8B1), and Niemann–Pick disease type A/B (SMPD1)." (PMID 33083013, 2020). "A previous study has reported ATP8B1 mutations L127P and E981K in patients with familial intrahepatic cholestasis type 1 (PFIC1), while the mutation I344F is identified in patients with benign recurrent intrahepatic cholestasis type 1 (BRIC1)." (PMID 32596364, 2020). "Mutations in the Atp8b1 gene are associated with progressive familial intrahepatic cholestasis type 1 (PFIC1, or Byler's disease)." (PMID 27689529, 2016). "The first type, called PFIC1 (Byler disease) is caused by mutations in the ATP8B1 gene (also designated FIC1)." (PMID 19133130, 2009). "Mutation of ATP8B1 in humans leads to progressive familial intrahepatic cholestasis type 1 (PFIC1)." (PMID 22438816, 2012). "Mutations in ATP8B1 (18q21-q22) cause variable cholestatic phenotypes ranging from progressive to benign recurrent forms (Progressive Familial Intrahepatic Cholestasis type 1, PFIC1, formerly Byler disease, and Benign Recurrent Intrahepatic Cholestasis type 1, BRIC1; OMIM 211600, 243300)." (PMID 23251605, 2012). "Pathogenic variants in the adenosine triphosphatase phospholipid transporting 8B1 (ATP8B1) gene cause progressive familial intrahepatic cholestasis type 1 (PFIC1) and benign recurrent intrahepatic cholestasis type 1 (BRIC1)." (PMID 35572954, 2022). "PFIC1 (also known as Byler disease) and BRIC are both caused by a mutation in the ATPase phospholipid transporting 8B1 (ATP8B1) gene, located on chromosome 18, which encodes for FIC1." (PMID 38055640, 2023). "Mutations in the ATP8B1 gene cause liver disease characterized by a continuous disease spectrum from intermittent Benign Recurrent Intrahepatic Cholestasis type 1 (BRIC1) to severe progressive Familial Intrahepatic Cholestasis type 1 (PFIC1)." (PMID 36293199, 2022). "One of the mouse models we used is the Atp8b1 mutant mouse, the animal model for progressive familial intrahepatic cholestasis type 1." (PMID 33731871, 2021). "The Atp8b1 mutant mouse is an excellent model for the human inherited disease, progressive familial intrahepatic cholestasis type 1 (PFIC1), which is (in humans), characterized by frequent and strong pruritus." (PMID 33731871, 2021).
progressive familial intrahepatic cholestasis type 1 (continued). "PFIC1 (ATP8B1 disease, OMIM #211600), formerly Byler's disease, is the consequence of a severe defect in the gene encoding ATPase, ATP8B1/FIC1 (familial intrahepatic cholestasis 1), localised in the long arm of the 18th chromosome (18q21)." (PMID 30148122, 2018). "Mutations in the ATP8B1 are responsible for two related liver diseases, known as benign recurrent intrahepatic cholestasis type 1 (BRIC1) and the more severe form progressive familial intrahepatic cholestasis type 1 (PFIC1)." (PMID 27458383, 2016). "Progressive familial intrahepatic cholestasis type 1 (PFIC1), a rare inherited autosomal recessive liver disease caused by mutations in ATP8B1, is characterized primarily by normal serum gamma-glutamyl transferase (GGT), intrahepatic cholestasis and jaundice in the first year of life." (PMID 25022842, 2014). "PFIC type 1, also known as Byler's disease, is an autosomal recessive disease caused by homozygous or compound heterozygous mutations of the ATP8B1 (adenosine triphosphatase, type 8B, member 1, formerly named FIC1) gene on chromosome 18 locus q21-22, which encodes the FIC1 protein." (PMID 37520499, 2023). "ATP8B1 has mostly been studied in progressive familial intrahepatic cholestasis type 1 (PFIC1)." (PMID 35159102, 2022).